MFGE8 (milk fat globule EGF and factor V/VIII domain containing)
Diseases named in the same sentence as MFGE8 in open-access papers (continued):
Sharing a sentence is not in itself a finding about the gene and the disease.
glioma (6 papers, 2016 to 2025). A benign or malignant brain and spinal cord tumor that arises from glial cells (astrocytes, oligodendrocytes, ependymal cells). "In this study, the mRNA expression profiles of DJ-1, GDF15, and MFGE8 genes were analyzed in glioma and meningioma tissues, and their potential associations with clinicopathological parameters were evaluated." (PMID 41009755, 2025). "In light of these findings, it was observed that the expression levels of DJ-1, GDF15, and MFGE8 genes may be associated with certain key clinical parameters in glioma and meningioma samples, which originate from different cellular lineages." (PMID 41009755, 2025). "In this study, the gene expression profiles of DJ-1, GDF15, and MFGE8 in tissue samples obtained from glioma and meningioma patient groups were found to be elevated compared to those in the control group." (PMID 41009755, 2025). "Silencing of Spp1 or Mfge8 expression in glioma cells prevented GAMs accumulation and reduced tumor growth in orthotopic rat gliomas." (PMID 40281508, 2025). "Overall, elevated expression levels of DJ-1, GDF15, and MFGE8 in glioma and meningioma samples, together with the observed PPI network connections, provide a framework for exploring their potential roles in tumour pathogenesis." (PMID 41009755, 2025). "According to TCGA and CGGA datasets, DJ-1, GDF15, and MFGE8 were found to be highly expressed in gliomas." (PMID 41009755, 2025). "The expression levels of the DJ-1, GDF15, and MFGE8 genes in glioma patients were elevated compared to those in the control group." (PMID 41009755, 2025). "In our study, a protein–protein interaction (PPI) network analysis was conducted using the GeneMANIA database to further evaluate the potential roles of DJ-1 (PARK7), GDF15, and MFGE8 genes in glioma and meningioma pathogenesis." (PMID 41009755, 2025). "In this study, significant and marked increases in the expression levels of the DJ-1, GDF15, and MFGE8 genes were detected in both glioma and meningioma tissues." (PMID 41009755, 2025). "In this study, the expression levels of DJ-1, GDF15, and MFGE8 genes were assessed in glioma and meningioma samples, and the resulting data were associated with clinical and pathological parameters, including sex, Ki-67 Pi, tumour diameter, and WHO tumour grade." (PMID 41009755, 2025). "Integrating PPI-based findings with gene expression data may contribute to understanding the possible mechanistic roles of DJ-1, GDF15, and MFGE8 in glioma and meningioma biology." (PMID 41009755, 2025). "Experimental studies have also demonstrated that MFGE8 may contribute to glioma progression by modulating the tumour microenvironment and promoting angiogenesis." (PMID 41009755, 2025). "MFGE8 (Milk Fat Globule-EGF Factor 8 Protein) contributes to extracellular matrix interactions and angiogenesis and has been implicated in tumour invasion and vascularization in both gliomas and meningiomas." (PMID 41009755, 2025). "When tumour diameter was evaluated in glioma patients, the expression levels of the DJ-1, GDF15, and MFGE8 genes were found to be elevated compared to those in the control group." (PMID 41009755, 2025). "Evaluation of tumour grades in glioma patients revealed that the expression levels of the DJ-1, GDF15, and MFGE8 genes were increased compared to those in the control group." (PMID 41009755, 2025). "In gliomas, statistically significant correlations were identified between the expression levels of DJ-1, GDF15, and MFGE8 and both tumour grade and the Ki-67 Pi." (PMID 41009755, 2025). "The integrin-blocking peptide (7aaRGD) was designed to block the binding of glioma-derived SPP1 and MFGE8 to αvβ3/αvβ5 integrins." (PMID 40281508, 2025). "When the Ki-67 Pi was evaluated in glioma patients, the expression levels of the DJ-1, GDF15, and MFGE8 genes were elevated compared to those in the control group." (PMID 41009755, 2025).
glioma (continued). "Furthermore, ROC analyses performed for glioma cases revealed that the AUC values for the DJ-1, GDF15, and MFGE8 genes were all below 0.7, with p-values above 0.05, indicating that these genes do not have sufficient diagnostic discriminatory power based on patient sex in glioma." (PMID 41009755, 2025).
Alzheimer disease (5 papers, 2018 to 2024). A progressive, neurodegenerative disease characterized by loss of function and death of nerve cells in several areas of the brain leading to loss of cognitive function such as memory and language. "Recent studies have shown that MFGE8, which promotes phagocytosis and inhibits inflammation, is an endogenous protective factor in response to brain infarction, Alzheimer’s disease, subarachnoid hemorrhage (SAH), and prion disease." (PMID 29535679, 2018). "Notably, MFGE8 expression was significantly increased in patients with Alzheimer’s disease (85.9 ± 3.7 years of age; 69% female) compared with controls without dementia (82.9 ± 5.0 years of age; 61% female)." (PMID 36385530, 2022). "In the mouse model, decreased expression of MFGE8 was observed in Alzheimer’s disease (AD)." (PMID 33597922, 2020). "Recent studies have shown that milk fat globule-epidermal growth factor-8 (MFGE8), which promotes phagocytosis and inhibits inflammation, is an endogenous protective factor in response to brain infarction, Alzheimer’s disease, subarachnoid hemorrhage, and prion disease." (PMID 29535679, 2018).
liver fibrosis (5 papers, 2017 to 2023). "At the same time, MFGE8 is a strong inhibitor of HSCs: it prevents liver fibrosis by downregulating the TGF-β type 1 receptor." (PMID 36831304, 2023). "Our previous study demonstrated a reduction in mouse liver fibrosis with the administration of recombinant MFGE8." (PMID 34829758, 2021).
ovarian carcinoma (5 papers, 2013 to 2025). A malignant neoplasm originating from the surface ovarian epithelium. "MFGE8-overexpressing tumors were of all grades (1 to 3), of all types, and of various metastatic status, thus MFGE8 overexpression could not be used as either a prognostic or a diagnostic marker of ovarian cancer." (PMID 23977342, 2013). "MFGE8 is considered to be a potential therapeutic target for ovarian cancer owing to its carcinogenic effect." (PMID 32766727, 2020). "To confirm the observation of MFGE8 mRNA overexpression at the protein level, we used two tumor microarrays generated in-house, containing 50 biopsies from ovarian cancer patients of all grades and types." (PMID 23977342, 2013). "Given the need for new treatments for this cancer, which often presents at advanced stage, we decided to further explore the roles of MFGE8 in ovarian carcinoma." (PMID 23977342, 2013). "The results presented here highlight a new type of cancer as a potential target for MFGE8-blocking therapies: ovarian carcinoma." (PMID 23977342, 2013). "The high proportion of tumors overexpressing MFGE8, however, prompted us to further explore its value as a therapeutic target for ovarian cancers." (PMID 23977342, 2013). "In order to select cell lines to assess the effect of anti-MFGE8 therapies, we first analyzed the mRNA expression level of MFGE8 and its receptors in a collection of human ovarian cancer cell lines." (PMID 23977342, 2013). "A previous study also suggested MFGE8 antibody as a novel therapeutic for ovarian carcinoma." (PMID 34440100, 2021). "Since MFGE8 has been shown in various cell types including some tumor cells, to promote adhesion, survival and/or epithelial-to-mesenchymal transition possibly leading to migration, we set up new in vitro assays to measure these physiological outcomes in the context of ovarian carcinoma." (PMID 23977342, 2013). "We confirmed MFGE8 protein secretion by ELISA analysis of the conditioned medium of two of the mRNA-expressing cell lines: SKOV-3 and IGROV-1, and we identified another ovarian carcinoma cell line, SHIN-3, which did not secrete detectable levels of MFGE8 in vitro." (PMID 23977342, 2013).
Stroke (5 papers, 2015 to 2024). Sudden impairment of blood flow to a part of the brain due to occlusion or rupture of an artery to the brain. "A beneficial role for MFGE8 has been demonstrated in stroke, neurodegenerative diseases (AD and PD), and traumatic brain injury." (PMID 38534785, 2024). "In stroke, MFGE8 promotes the proliferation of neural stem cells and their migration toward ischemic brain tissues." (PMID 38534785, 2024). "Stroke was induced in wild-type (Wt) and MFG-E8-deficinet (Mfge8-/-) mice by transient middle cerebral artery occlusion (tMCAO)." (PMID 25867181, 2015).
subarachnoid hemorrhage (5 papers, 2018 to 2024). A serious neurological disorder characterized by intracranial hemorrhage into the subarachnoid space. "The MFGE8 protein also has the ability to inhibit the production of pro-inflammatory cytokines or down-regulate the expression of apoptotic protein genes in models of cerebral ischemia and subarachnoid hemorrhage." (PMID 38534785, 2024).
cardiac hypertrophy (4 papers, 2020 to 2023). "MFGE8, a secreted glycoprotein, is associated with a variety of pathophysiological processes, including anti-inflammatory, antifibrosis, antiatherosclerosis, and inhibition of cardiac hypertrophy." (PMID 32695227, 2020). "While Ccl7 plays a critical role in CCR2-dependent monocyte recruitment to the heart, MFGE8 is involved in cardiac hypertrophy, cardiac fibrosis, and removal of dead cells." (PMID 37563727, 2023). "In previous studies, knockout of Mfge8 in mice exacerbates pressure overload‐induced cardiac hypertrophy and leads to remarkable inflammatory responses and an enormous reduce in survival after MI." (PMID 32945126, 2020).
cognitive decline (4 papers, 2022 to 2025). "Unlike GALNT2 and TRMT2A, whose evidence of involvement in AD are limited, MFGE8 (a.k.a. medin) is strongly linked to AD, as it interacts directly with amyloid-β to promote its aggregation and it is associated with cognitive decline." (PMID 40602528, 2025). "A small, 50 amino acid polypeptide fragment of MFGE8 (medin) also co-localized with vascular Aβ, and higher vascular MGFE8 expression levels have been associated with an increased degree of cognitive decline in AD." (PMID 38745197, 2024). "Mfge8 is shown to co-localize with vascular-amyloid deposits, with AD patients having higher levels and cognitive decline regardless of plaque and tau pathology." (PMID 37174641, 2023).
colorectal cancer (4 papers, 2014 to 2024). A primary or metastatic malignant neoplasm that affects the colon or rectum. "Both clinical studies underscored the upregulation of MFGE8 expression in colorectal cancer tumor tissues, and patients with high MFGE8 expression had poorer prognoses." (PMID 38802814, 2024). "Additionally, the effect of MFGE8 on colorectal cancer cell migration, invasion, and epithelial-to-mesenchymal transition was found to be partially dependent on the PI3K/AKT signaling pathway." (PMID 38802814, 2024). "The relationship between overall survival (OS) in colorectal cancer patients and the expression of miRs, which may target EZH2 and MFGE8 and have been linked to cancer, was examined using plasma and FFPE samples." (PMID 25081869, 2014). "Furthermore, higher miR-26a expression levels, and lower miR-124-5p expression levels were associated with a lower probability of OS; therefore the expression of MFGE8, miR-26a and miR-124-5p in plasma may be used as biomarkers to determine the prognosis of colorectal cancer patients." (PMID 25081869, 2014).
glomerulonephritis (4 papers, 2012 to 2023). A renal disorder characterized by damage in the glomeruli. "The fact that Mfge8−/− mice develop a spontaneous late onset lupus-like disease and glomerulonephritis suggests that rs4945 and rs1878326 lead to a decrease of MFGE8 bioactivity, that would explain their association with the human disease." (PMID 22438901, 2012). "MFGE8 mediated phagocytosis induces a regulatory T cell response and Mfge8−/− mice develop spontaneous late onset lupus-like disease and glomerulonephritis." (PMID 22438901, 2012).
injury (4 papers, 2020 to 2024). Damage inflicted on the body as the direct or indirect result of an external force, with or without disruption of structural continuity. "For instance, MFGE8 reduces apoptosis via integrin β3/FAK/PI3K/Akt signaling pathway in rat model of traumatic brain injury." (PMID 39128910, 2024).
lung carcinoma (4 papers, 2021 to 2025). "The titer of autoantibodies against MFGE8, NRAS, PTP4A1, RRAS2 was measured in serum of 80 esophagus cancer cases (ECs), 80 hepatocellular carcinoma cases (HCCs), 80 lung cancer cases (LCs), and 80 healthy controls by ELISA." (PMID 33718231, 2021). "However, given that lung cancers secrete multiple additional factors (e.g., HSPA1A, MFGE8, ANXA4), our approach allows us to study and dissect the role of tumor‐derived EVs independent of other secreted factors." (PMID 40788065, 2025).
myocardial infarction (4 papers, 2017 to 2023). Gross necrosis of the myocardium, as a result of interruption of the blood supply to the area, as in coronary thrombosis. "In these two pathological environments, endogenous MFGE8, as a key cofactor of VEGF, activates Akt pathway to stimulate angiogenesis to promote tumour development or improve cardiac remodelling after myocardial infarction." (PMID 32945126, 2020).
prion disease (4 papers, 2017 to 2021). A transmissible disease that is caused by a protein that is able to induce abnormal folding of normal cellular proteins, leading to characteristic spongiform brain changes, which are associated with neuronal loss without an inflammatory response. "In prion diseases, microglia can clear the CNS of PrPSc with the collaboration of astrocytes, which release lactadherin (MFGE8), a protein that tags PrPSc -containing apoptotic cells for phagocytosis." (PMID 34751640, 2021). "In mice, Mfge8 genetic ablation results in reduced clearance of apoptotic cells, increased PrPSc levels and prion titers and accelerated prion disease." (PMID 28545141, 2017). "Sirpa and Cd47 mRNA levels showed some fluctuations during the progression of prion diseases, with some degree of variation based on mouse and prion strain combination, and the same occurred also to Mfge8 levels." (PMID 28545141, 2017). "In addition, we analysed Sirpa, Cd47, Aif1, Trem2 and Mfge8 mRNA levels selectively in hippocampus and cerebellum at different time points during the progression of prion disease using RNA sequencing." (PMID 28545141, 2017).
prostate carcinoma (4 papers, 2019 to 2024). A carcinoma that arises from epithelial cells of the prostate gland. "The serum level of Mfge8 is higher in prostate cancer patients than in control subjects." (PMID 31088536, 2019).
rheumatoid arthritis (4 papers, 2016 to 2022). A chronic, systemic autoimmune disorder characterized by inflammation in the synovial membranes and articular surfaces. "Several studies have shown that MFGE8 is a novel anti-inflammatory factor in multisystem diseases, such as neonatal sepsis, hepatic steatosis, rheumatoid arthritis and kidney injury." (PMID 34950025, 2021).
triple-negative breast carcinoma (4 papers, 2013 to 2024). An invasive breast carcinoma which is negative for expression of estrogen receptor (ER), progesterone receptor (PR), and human epidermal growth factor receptor 2 (HER2). "MFGE8 encodes Milk fat globule-EGF factor 8 and its reduction was shown to inhibit triple-negative breast cancer cell viability and migration." (PMID 38940181, 2024). "Our results thus confirm MFGE8 as a promising target for an antibody-based strategy aiming at blocking tumor growth of triple-negative breast cancers." (PMID 23977342, 2013).
acute pancreatitis (3 papers, 2021 to 2023). An acute inflammatory process that leads to necrosis of the pancreatic parenchyma. "Knocking out Mfge8 in mice exacerbated the severity of cerulein-induced acute pancreatitis and delayed its resolution." (PMID 33806041, 2021). "In contrast, administration of recombinant MFG-E8 attenuated cerulein-induced acute pancreatitis and promoted repair of pancreatic injury in Mfge8 KO mice." (PMID 33806041, 2021). "We next investigated the role of MFG-E8 in the pathogenesis of cerulein-induced acute pancreatitis using Mfge8 KO mice." (PMID 33806041, 2021). "To understand the role of MFG-E8 in the development of pancreatitis, we compared the severity of cerulein-induced acute pancreatitis in Mfge8 KO vs. WT mice administered 10 hourly IP injections of cerulein (50 μg/kg)." (PMID 33806041, 2021). "In contrast, Mfge8 KO mice treated with rMFG-E8 exhibited less severe inflammatory cell infiltration and reduction of acinar cell necrosis in the pancreas, suggesting that rMFG-E8 attenuated cerulein-induced acute pancreatitis in Mfge8 KO mice." (PMID 33806041, 2021). "Mfge8 KO mice treated with cerulein and saline developed severe acute pancreatitis characterized by diffuse severe edema, marked inflammatory cell infiltration, and abundant vacuolization and necrosis in 11 h after the first cerulein injection." (PMID 33806041, 2021). "Mfge8 KO mice were injected with rMFG-E8 or saline (control) and then subjected to experimental acute pancreatitis with cerulein injections." (PMID 33806041, 2021). "Next, we examined whether the administration of recombinant MFG-E8 (rMFG-E8) can rescue the delayed recovery phenotype of Mfge8 KO with cerulein-induced acute pancreatitis." (PMID 33806041, 2021). "In the present study, we found that Mfge8 expression is not only sustained in ductal epithelial cells but activated in acinar cells as well as endothelial cells of interlobular blood vessels during acute pancreatitis." (PMID 33806041, 2021). "Administration of rMFG-E8 rescued Mfge8 KO mice from cerulein-induced severe acute pancreatitis." (PMID 33806041, 2021). "However, we did not note any change in Mfge8 gene expression in the pancreatic islets in mice with acute pancreatitis." (PMID 33806041, 2021). "At 48 h, Mfge8 gene expression was induced not only in acinar cells and ductal epithelial cells but also in endothelial cells of interlobular blood vessels, suggesting that MFG-E8 is diffusely present in pancreatic tissue during the late acute and recovery phase of acute pancreatitis." (PMID 33806041, 2021).
asthma (3 papers, 2017 to 2022). "Mfge8‐deficient mice (Mfge8−/−) developed exaggerated AHR in an experimental asthma model, suggesting that Mfge8 may protect against the exaggerated AHR." (PMID 32355562, 2020).
esophageal squamous cell carcinoma (3 papers, 2022 to 2025). Esophageal squamous cell carcinoma (ESCC) is a type of esophageal carcinoma (EC) that can affect any part of the esophagus, but is usually located in the upper or middle third. "The abundant MFGE8 expression in esophageal squamous cell carcinoma might have a negative influence on the long-term survival of patients after chemotherapy." (PMID 36059952, 2022).
Hepatic steatosis (3 papers, 2021 to 2023). Steatosis is a term used to denote lipid accumulation within hepatocytes. "In addition, the modulator MFGE8, one of the cytosolic burial signals, promotes enterocyte triglyceride hydrolase activity, reduces postprandial lipids, decreases lipid accumulation in enterocytes, and ameliorates hepatic steatosis and inflammation." (PMID 37886125, 2023).
Hypertension (3 papers, 2019 to 2022). The presence of chronic increased pressure in the systemic arterial system. "Therefore, MFGE8 could be a potential risk factor for hypertension." (PMID 30967125, 2019).